DANCR (differentiation antagonizing non-protein coding RNA)
Diseases named in the same sentence as DANCR in open-access papers (continued):
Sharing a sentence is not in itself a finding about the gene and the disease.
prostate carcinoma (continued). "Therefore we want to determine whether DANCR knockdown could affect the effect of enzalutamide on prostate cancer cell invasion and migration." (PMID 27191265, 2016). "We further investigated whether DANCR affects AR function on the invasion of prostate cancer cells." (PMID 27191265, 2016). "Moreover, we determined whether DNACR regulated cell invasion synergistically with EZH2 and whether DANCR affected the effect of androgen-AR signaling and enzalutamide, an inhibitor of AR, on migration and invasion of prostate cancer cells." (PMID 27191265, 2016). "Taken together, our results support that AR could inhibit some metastasis-promoting pathways or molecules in prostate cancer, and suggest that knockdown of DANCR could lessen the side effect of AR inhibitor, which may be useful in the treatment of prostate cancer." (PMID 27191265, 2016). "DANCR can also target miR-185-5p to increase expression of LIM and SH3 protein 1 promoting prostate cancer through the FAK/PI3K/AKT/GSK3β/snail axis." (PMID 37025585, 2023). "A number of well-known oncogenic lncRNAs in other cancers such as DANCR, MALAT1, CCAT1, PVT1, TUG1 and NEAT1 have also been shown to act as oncogenes in prostate cancer." (PMID 37025585, 2023). "For example, in prostate cancer DANCR was identified as a downstream gene of C-MYC, and DANCR promoted cell cycle progression and cell proliferation by repressing the expression of CDKN1A24." (PMID 33414433, 2021). "And DANCR regulated the expression of E-cadherin, N-cadherin and NLRP3 by targeting miR-135a-5p in prostate cancer." (PMID 33123287, 2020). "DANCR served as a ceRNA of miR-34a-5p, leading to the derepression of miR-34a-5p target JAG1 to enhance DTX resistance of prostate cancer." (PMID 33123287, 2020). "DANCR was also upregulated in lung cancer 20, gastric cancer 21, triple‐negative breast cancer 22, and prostate cancer." (PMID 31515968, 2020). "Although DANCR expression elevates in prostate cancer, the clinical relevance between DANCR and prostate cancer is still not clear." (PMID 27191265, 2016). "On the other hand, DANCR knockdown facilitated the upregulation of TIMP2/3 and the suppression of invasion and migration by androgen-AR, while DANCR knockdown decreased the promotion of invasion and migration in prostate cancer cells by enzalutamide treatment." (PMID 27191265, 2016). "Moreover, DANCR could interact with epigenetic gene silencer, EZH2, to reduce the expression of TIMP2 and TIMP3 and promote prostate cancer invasion and migration." (PMID 37215458, 2023). "However, the biological functions and significance of DANCR in other tumors including prostate cancer have not been established yet." (PMID 27191265, 2016). "In addition, we detected the expression level of DANCR in prostate cancer cell lines, and consistently we found that DANCR is up-regulated in prostate cancer cell lines compared with RWPE1, which is an immortalized normal prostate epithelial cell line." (PMID 27191265, 2016).
colorectal cancer (20 papers, 2016 to 2024). A primary or metastatic malignant neoplasm that affects the colon or rectum. "The crucial role of TRIM24 in colorectal cancer cell proliferation is facilitated by the DANCR/KAT6A complex, which enhances TRIM24 association with H3K23ac and subsequently recruits YAP to chromatin, contributing to increased cell proliferation." (PMID 39160596, 2024). "Another research provided evidence that TRIM24 interaction with H3K23ac, mediated by the DANCR/KAT6A complex, enhances oncogenic processes associated with the YAP signaling pathway in colorectal cancer." (PMID 39160596, 2024). "In colorectal cancer cells, DANCR has been shown to affect activity of miR-125b-5p/HK2 axis to induce resistance to cisplatin through induction of anaerobic glycolysis." (PMID 35590326, 2022). "Most notably, the interaction between DANCR and the important oncogenic lncRNA MALAT1 has been found to induce resistance to doxorubicin-associated apoptosis in colorectal cancer cells." (PMID 35590326, 2022). "In summary, these findings provide new insight into the function and the working mechanism of DANCR in colorectal cancer cells." (PMID 33414433, 2021). "In this work, we reported lncRNA DANCR repressed by Dox was closely correlated with colorectal cancer cell apoptosis." (PMID 33414433, 2021). "Our work indicated that the major function of DANCR in colorectal cancer resided in the regulation of apoptosis." (PMID 33414433, 2021). "In this work, we revealed DANCR was a Dox-suppressed target, which was involved in the regulation of apoptosis in colorectal cancer." (PMID 33414433, 2021). "Although these studies provided early evidence depicting the oncogenic role of DANCR in colorectal cancer, the major function and detailed working mechanism of DANCR in the disease need further exploration." (PMID 33414433, 2021). "Zeng group reported that the overexpression of DANCR in colorectal cancer was correlated with cell proliferation and cancer metastasis." (PMID 33414433, 2021). "DANCR had also been proven to promote the proliferation and metastasis of colorectal cancer via miR-577 sponging." (PMID 33329694, 2020). "For example, remarkably high expression of DANCR was observed in patients with colorectal cancer, and overexpressed DANCR increased HSP27 levels and promoted proliferation and metastasis through miR‐577 sponging." (PMID 31515968, 2020). "The discovery that DANCR over-expressed in colorectal cancer promoted tumor progression and predicted poor prognosis introduced the study of DANCR into the field of cancer." (PMID 31799189, 2019). "DANCR has also been identified as a molecular sponge mediating miR-758-3p17 and miR-57718 in non-small cell lung cancer and colorectal cancer, respectively." (PMID 30518934, 2018). "Thus, lncRNA DANCR up-regulation is associated with aggressive progression and poor prognosis in colorectal cancer and may function as an independent marker for predicting the clinical outcome of colorectal cancer patients." (PMID 27148353, 2016). "In addition, lncRNA DANCR was highly expressed in colorectal cancer (CRC) tissues compared to normal tissues, and its overexpression was negatively associated with CRC patient survival." (PMID 35150011, 2022). "So far only a few studies have explored the function of DANCR in colorectal cancer." (PMID 33414433, 2021). "We further found that the DANCR/KAT6A complex promoted the association of TRIM24 with H3K23ac, thereby inducing TRIM24‐mediated recruitment of YAP to the chromatin, and promoting proliferation of colorectal cancer cells." (PMID 32677374, 2020). "Our data also suggest that DANCR/KAT6A promotes the association between TRIM24 and H3K23ac, thereby enhancing the TRIM24‐mediated recruitment of YAP to the chromatin, resulting in the proliferation of colorectal cancer cells." (PMID 32677374, 2020).
colorectal cancer (continued). "To gain insights into the precise role of the DANCR/KAT6A complex in mediating the function of TRIM24 in colorectal carcinoma, we inhibited the expression of DANCR or KAT6A in both SW620 and HT29 cells, and found that both mRNA and protein expression of YAP were inhibited." (PMID 32677374, 2020). "Thus, the DANCR/KAT6A complex upregulates TRIM24 in colorectal cancer." (PMID 32677374, 2020). "We elucidated a previously unknown molecular mechanism involving DANCR/KAT6A‐mediated association of TRIM24 with H3K23ac, which subsequently results in enhancement of the oncogenic processes associated with the YAP signaling pathway in colorectal cancer." (PMID 32677374, 2020). "We found that the DANCR/KAT6A complex upregulated TRIM24, and promoted cell proliferation in colorectal cancer." (PMID 32677374, 2020). "DANCR and KAT6A, long non‐coding RNA (lncRNA) molecules, have been reported to form a complex which mediates cell proliferation in colorectal cancer." (PMID 32677374, 2020). "A previous study revealed that DANCR interacts with KAT6A, which promotes proliferation of colorectal cancer cells." (PMID 32677374, 2020). "DANCR acts as a miRNA sponge in colorectal cancer (CRC) cells, which is the most common role that DANCR plays in cancer development." (PMID 31799189, 2019). "TRIM24 is initially activated by the DANCR/KAT6A complex, thereby binding with H3K23ac and subsequently inducing TRIM24‐mediated recruitment of YAP to the chromatin, which ultimately promotes the proliferation of colorectal cancer cells." (PMID 32677374, 2020). "Recent studies demonstrated that DANCR directly interacts with miR-758-3p17 and miR-57718 in non-small cell lung cancer and colorectal cancer, respectively." (PMID 30518934, 2018). "However, the contribution of DANCR to the tumorigenesis of colorectal cancer and its working mechanism have not been fully elucidated." (PMID 33414433, 2021). "Besides, lncRNA DANCR could promote the HSP27 expression and its mediation of metastasis via miR-577 sponging in colorectal cancer." (PMID 30910838, 2021). "TRIM24 was shown to be oncogenic in colorectal cancer, but the relationship between the DANCR/KAT6A complex and TRIM24 in colorectal cancer had not previously been investigated." (PMID 32677374, 2020).
gastric cancer (19 papers, 2018 to 2022). A primary or metastatic malignant neoplasm involving the stomach. "Taken together, these data indicate that the expression level of DANCR is elevated in the tumor tissues and serum of gastric cancer patients and the increased expression of DANCR is associated with the malignant progression of gastric cancer." (PMID 29416741, 2018). "Our findings indicate that DANCR plays an oncogenic role in gastric cancer and have the potential to serve as a novel diagnostic biomarker." (PMID 29416741, 2018). "Taken together, our findings suggest that DANCR promotes the progression of gastric cancer and have the potential to serve as a novel diagnostic biomarker." (PMID 29416741, 2018). "The elevated expression of DANCR is associated with malignant progression of gastric cancer." (PMID 29416741, 2018). "DANCR expression is an important factor leading to drug resistance in colon cancer, gastric cancer, and other tumors." (PMID 36189298, 2022). "Otherwise, our previous research showed that the expression of DANCR was higher in the serum of gastric cancer patients." (PMID 33123287, 2020). "Further research showed that DANCR expression remained high in cisplatin (DDP) resistant gastric cancer tissues or cells." (PMID 33123287, 2020). "Our previous study found that DANCR knockdown decreased while DANCR overexpression increased the expression of β-catenin in gastric cancer cells." (PMID 33123287, 2020). "In summary, these results suggest that DANCR overexpression promotes the proliferation, migration and invasion of gastric cancer cells." (PMID 29416741, 2018). "DANCR promotes gastric cancer cell proliferation, migration and invasion by accelerating cell cycle progression, inhibiting apoptosis, and inducing EMT." (PMID 29416741, 2018). "In contrast to the previous stomach cancer study, a down-regulation of DANCR in GC was found in the present study using the GEO and qPCR data, which however was not validated in the TCGA dataset." (PMID 30518158, 2018). "DANCR is activated by SALL4 in gastric cancer cells and exerted its oncogenic activities through the activation of β-catenin pathway." (PMID 29416741, 2018). "Another study in gastric cancer cells has shown that KLF5 activates DANCR transcription." (PMID 35590326, 2022). "Expression of DANCR has been found to be high in cisplatin-resistant gastric cancer cells." (PMID 35590326, 2022). "LncRNA-LET was a target gene of DANCR, and DANCR could associate with enhancer of zeste homolog 2 (EZH2) and HDAC3 to epigenetically silence lncRNA-LET, then regulate gastric cancer migration and invasion." (PMID 33123287, 2020). "Moreover, DANCR was indicated to contribute to migration and invasion in gastric cancer cells via inhibition of lncRNA-LET." (PMID 32099526, 2020). "Our findings, together with those from the others, suggest that DANCR may promote gastric cancer progression via regulating cell proliferation, migration and invasion." (PMID 29416741, 2018). "Moreover, expression of DANCR in gastric cancer can be induced by SALL4." (PMID 35590326, 2022). "DANCR could activate β-catenin to promote gastric cancer progression." (PMID 33123287, 2020). "In addition, DANCR knockdown suppressed gastric cancer growth in vivo." (PMID 29416741, 2018). "We reported in this study that DANCR upregulated the expression of β-catenin and activated its downstream target genes in GC cells, promoting gastric cancer cell proliferation, migration and invasion." (PMID 29416741, 2018). "In addition, the promoting role of DANCR in GC cell proliferation, migration and invasion were also decreased by β-catenin knockdown in GC cells, suggesting that DANCR activates β-catenin to promote gastric cancer progression." (PMID 29416741, 2018). "To determine the functional roles of DANCR in gastric cancer, we knocked down DANCR expression in GC cell lines MGC-803 and BGC-823 by using shRNA." (PMID 29416741, 2018).
gastric cancer (continued). "To further demonstrate the oncogenic roles of DANCR in gastric cancer, we overexpressed DANCR in MKN45 cells that harbor relatively low level of DANCR." (PMID 29416741, 2018). "For further validation TCGA RNA-seq expression data for PCAT18, DANCR, and LINC01133 in stomach cancer and normal tissues were analyzed." (PMID 30518158, 2018). "It was suggested that in gastric cancer cells, DANCR could be activated by SALL4, which could bind to the promoter of DANCR." (PMID 34722539, 2021). "DANCR (anti-differentiation noncoding RNA) is a newly identified lncRNA in human cancer, however, its functional roles and clinical value in gastric cancer (GC) remains unknown." (PMID 29416741, 2018). "Furthermore, DANCR up-regulation could up-regulate expression levels of MDR1 and MRP1 in cisplatin resistant gastric cancer cells." (PMID 35590326, 2022). "In addition, DANCR overexpression could upregulate the expression of MDR1 and MRP1 to accelerate the multidrug resistance (MDR) of gastric cancer." (PMID 33123287, 2020). "We found that the upregulation of DANCR was positively correlated with tumor size, lymphatic metastasis, invasion depth and advanced TNM stage, indicating that DANCR overexpression may contribute to the development and progression of gastric cancer." (PMID 29416741, 2018).
lung carcinoma (14 papers, 2014 to 2024). "In other studies, DANCR was reported to have an oncogenic role and was associated with the progression of various tumors, including lung cancer and ovarian cancer." (PMID 35235755, 2022). "Knockdown of DANCR reduced lung cancer cell stemness and migration but increased liver cancer cell stemness, facilitating intrahepatic and extrahepatic tumour colonization." (PMID 38877534, 2024). "Another study has identified the impact of DANCR/miR-1225-3p/ErbB2 axis in the regulation of metastasis of lung cancer cells." (PMID 35590326, 2022). "In lung cancer cells, DANCR expression levels have been negatively correlated with levels of miR-216a." (PMID 35590326, 2022). "DANCR over-expression has also been detected in lung cancer, principally in high-grade samples and aggressive tumors." (PMID 35590326, 2022). "LncRNAs are overexpressed in a variety of cancers, including lncRNA DGCR5 and DANCR in lung cancer, lncRNA H19 in melanoma, and lncRNA TUG1 in ovarian cancer." (PMID 34131102, 2021). "The DANCR overexpression promoted cell proliferation and colony formation in vitro, and DANCR interference effectively suppressed lung cancer progression both in vitro and in vivo." (PMID 33123287, 2020). "Several lncRNAs such as H19, MALAT1, and DANCR act as oncogenes in lung cancer by interacting with miRNAs." (PMID 33412752, 2020). "We found that lung cancer cell motility was obviously inhibited by the down‐regulation of DANCR, and cotransfection with the miR‐496 inhibitor rescued this effect." (PMID 29266795, 2018). "Moreover, invasive properties of lung cancer cells are regulated by DANCR through suppression of miR-216 and subsequent activation of Wnt/β-Catenin signals." (PMID 35590326, 2022). "However, the role of DANCR in lung cancer still needs to be explored and its function remains to be characterized." (PMID 29266795, 2018). "These experiments demonstrate that DANCR positively regulates the development of lung cancer." (PMID 29266795, 2018). "In addition, lncRNAs such as DANCR, LINC00336, MNX1-AS1, LINC00673, SNHG4, LEF1-AS1, UCA1 (urothelial carcinoma-associated 1), SNHG1, and PTAR act as ceRNAs for miRNAs and exhibit oncogenic functions in lung cancer cells." (PMID 33412752, 2020). "We also examined whether DANCR affected lung cancer cell migration and invasion." (PMID 29266795, 2018). "Although DANCR is generally considered an oncogenic factor in most cancers, it is considered a tumour suppressor in RCC, and its role in some cancers, such as lung cancer and PTC, remains controversial." (PMID 38877534, 2024). "Thus, DANCR might be a key regulator of lung cancer progression and used as a promising biomarker." (PMID 34722539, 2021).